CRIP1 (cysteine rich protein 1)
Diseases named in the same sentence as CRIP1 in open-access papers (continued):
Sharing a sentence is not in itself a finding about the gene and the disease.
colorectal cancer (6 papers, 2013 to 2025). A primary or metastatic malignant neoplasm that affects the colon or rectum. "CORO6 and CRIP1 were barely detected in the plasma from colorectal cancer (CRC) and hepatocellular carcinoma (HCC) patients (3.9%, 9 of 229 for CRC and 9.5%, 4 of 42 for HCC), suggesting that these two markers were not hypermethylated in cancers." (PMID 35062960, 2022). "GSK-3β is an important signal transduction molecule in the Wnt/β-catenin signaling pathway, and CRIP1 promotes EMT through zinc-induced p-GSK-3β in colorectal cancer." (PMID 33584272, 2020). "CRIP1 promotes its ubiquitination and degradation by interacting with Fas and inhibits the formation of signal transduction complexes and subsequent caspase activation, thereby inhibiting cell apoptosis in colorectal cancer." (PMID 40118853, 2025). "In colorectal cancer, CRIP1 could facilitate the 5-FU drug resistance by downregulating the Fas and Fas-mediated apoptosis-related proteins’ expression." (PMID 35938037, 2022). "Conversely, in colorectal cancer cells, excessive Zn2+ supplementation activates the GSK 3/mTOR signaling pathway and promotes EMT, CRIP1 silencing inhibits this signaling pathway and reverses this response." (PMID 40118853, 2025). "CRIP1 (cysteine-rich intestinal protein 1) belongs to the LIM/double-zinc finger protein family and has been shown to be overexpressed in several tumor types, including breast, cervical, prostate, pancreatic, and colorectal cancers." (PMID 23570421, 2013).
osteosarcoma (6 papers, 2011 to 2025). A usually aggressive malignant bone-forming mesenchymal neoplasm, predominantly affecting adolescents and young adults. "Conversely, in osteosarcomas, CRIP1 expression was more frequently found in patients with long-term survival and without metastases, indicating a favorable prognostic effect." (PMID 23570421, 2013). "In search of new and reliable biomarkers we recently identified cysteine-rich intestinal protein 1 (CRIP1) to have significant prognostic impact in gastric cancer and therefore decided to investigate its role also in osteosarcoma." (PMID 22202598, 2011). "CRIP1 therefore seems to represent a promising new biomarker in osteosarcoma patients which should be considered for a prospective validation." (PMID 22202598, 2011). "For this purpose we analyzed 223 pretherapeutic and well characterized osteosarcoma samples for their immunohistochemical expression of CRIP1 and correlated our findings with clinico-pathological parameters including follow-up, systemic spread and response to chemotherapy." (PMID 22202598, 2011). "In the present study, however, we identified CRIP1 to be strongly associated with a favorable outcome and as a statistically significant negative predictor of systemic spread in osteosarcoma." (PMID 22202598, 2011). "Taken together, we identified CRIP1 as a new and promising biomarker in osteosarcoma." (PMID 22202598, 2011). "Consequently, CRIP1 should be validated prospectively to proof its prognostic reliability and, nonetheless, a potential role in response prediction in osteosarcoma patients." (PMID 22202598, 2011). "Nevertheless, osteosarcomas are not the first malignant tumors in which a tumor suppressor function of CRIP1 is highly suggestive since also in carcinomas of the pancreas a downregulation of CRIP1 has been reported." (PMID 22202598, 2011).
prostate carcinoma (6 papers, 2011 to 2026). A carcinoma that arises from epithelial cells of the prostate gland. "Additionally, Tcfap2c induced the expression of cancer-associated markers such as, CRIP1 a putative target gene of TFAP2 in prostate cancer." (PMID 21779369, 2011). "Functionally, CRIP1 knockdown restored docetaxel sensitivity, reduced clonogenic survival and migratory capacity, and enhanced docetaxel-induced apoptosis in resistant prostate cancer cells." (PMID 41988531, 2026). "For example, in prostate cancer, CRIP1 upregulation increases orthotopic prostate tumor growth." (PMID 40118853, 2025). "At the same time, studies have found that CRIP1 and CRIP2 are regulated by hormones such as glucocorticoids and thyroxine, which further provides a new perspective on their potential role in hormone-dependent diseases such as breast and prostate cancers." (PMID 40118853, 2025).
hepatocellular carcinoma (4 papers, 2022 to 2026). A malignant tumor that arises from hepatocytes. "More recently, CRIP1 has been implicated in several cancers, including hepatocellular carcinoma, acute myeloid leukemia, multiple myeloma, and melanoma, where it can act as either a pro-tumorigenic factor or a tumor suppressor." (PMID 41972184, 2026). "Overexpression of CRIP1 in hepatocellular carcinoma (HCC) promotes the invasion ability of HCC cells and induces EMT." (PMID 40118853, 2025).
multiple myeloma (4 papers, 2024 to 2026). "In multiple myeloma, the high expression of CRIP1 promotes cell proliferation and invasion, which is an independent risk factor for prognosis." (PMID 40118853, 2025). "CRIP1 enhances proteasome activity and autophagy by binding to the ubiquitin specific peptidase 7 (USP7) and the proteasome activating protein 200 (PA200) in multiple myeloma." (PMID 40118853, 2025). "In addition, CRIP1 has been shown to be significantly negatively correlated with ASV333 in this study, and it participates in the pathogenesis of multiple myeloma through dual regulation of proteasome and autophagy." (PMID 40124891, 2025). "The results suggest that three genes, CRIP1, HIST1H1C and RNF125, are significantly overexpressed in myeloma cell lines and may contribute to the poor prognosis in malignant plasma cell samples, whereas C1orf56 and S100A6 may contribute to the poor prognosis in microenvironmental cell samples." (PMID 38278930, 2024).
Stroke (4 papers, 2024 to 2025). Sudden impairment of blood flow to a part of the brain due to occlusion or rupture of an artery to the brain. "Multiple studies have linked CRIP1 expression to hypertension and stroke risk possibly by regulating interactions with cytoskeletal proteins leading to altered monocyte migration and invasion." (PMID 41282800, 2025). "Whole transcriptome analysis confirmed that the expression level of CRIP1 was strongly correlated with hypertension at the population level, and the increase of CRIP1 levels in the blood circulation of patients with hypertension was accompanied by an increased risk of stroke." (PMID 40118853, 2025). "Cysteine-rich protein 1 (Crip1) expression in MΦ and Mo has been shown to participate in the regulation of the immune response, and has an correlation with an increased risk for stroke." (PMID 40777042, 2025). "CRIP1 expression has been associated with cardiac hypertrophy and an increased risk of stroke." (PMID 37938355, 2024).
acute myeloid leukemia (3 papers, 2022 to 2026). Acute myeloid leukemia (AML) is a group of neoplasms arising from precursor cells committed to the myeloid cell-line differentiation. "CRIP1 silencing in acute myeloid leukemia (AML) induces apoptosis and growth cycle arrest." (PMID 40118853, 2025).
Hypertension (3 papers, 2022 to 2025). The presence of chronic increased pressure in the systemic arterial system. "CRIP1-positive circulating and splenic monocytes have been reported to play an important role in the inflammatory process associated with hypertension, and CRIP1 may influence the interaction of the immune system and the pathogenesis of hypertension." (PMID 36506327, 2022). "Human cohort studies have found that the expression of CRIP1 in splenic monocytes/macrophages and circulating monocytes is significantly affected by angiotensin II and is closely related to the pathogenesis of hypertension." (PMID 40118853, 2025). "In the pathogenesis of human hypertension, angiotensin II upregulates CRIP1 expression in splenic monocytes/macrophages and blood monocytes." (PMID 40118853, 2025). "CRIP1 may be involved in the development of hypertension through the immune system, especially monocytes." (PMID 40118853, 2025).
pancreatic carcinoma (3 papers, 2011 to 2025). "Subsequently, upregulation of CRIP1 was also detected in colorectal, cervical and prostatic cancer whereas downregulation was demonstrated in pancreatic carcinoma." (PMID 22202598, 2011). "In the last years, deregulated CRIP1 expression was reported to characteristically occur in several malignant tumors, including breast, cervical, prostatic, colorectal, and pancreatic cancer." (PMID 22202598, 2011). "However, evidence of prognostic impact of CRIP1 in pancreatic cancer is still lacking." (PMID 22202598, 2011).
pancreatic ductal adenocarcinoma (3 papers, 2024 to 2025). An infiltrating adenocarcinoma that arises from the epithelial cells of the pancreas. "The results of pancreatic ductal adenocarcinoma showed that the tumor cells with high CRIP1 expression had a high degree of infiltration of myeloid-derived suppressor cells(MDSC) and formed an immunosuppressive tumor microenvironment." (PMID 40118853, 2025). "In pancreatic ductal adenocarcinoma, NF-κB is activated by the pro-oncogenic protein cysteine-rich intestinal protein 1 (CRIP1), which results in the transcriptional induction of the chemokines CXCL1 and CXCL5 and the recruitment of MDSCs to promote immunosuppression." (PMID 40562870, 2025).
sarcoma (3 papers, 2020 to 2025). A usually aggressive malignant neoplasm of the soft tissue or bone. "After performing validation in both TCGA dataset and GEO dataset GSE17679, we extracted a group of immune-related genes, including NR1H3, VAMP5, GIMAP2, GBP2, HLA-E and CRIP1 that were most significant to predict good outcomes in sarcoma patients." (PMID 33316779, 2020).
thyroid cancer (3 papers, 2019 to 2025). "In thyroid cancer, CRIP1 silencing cells undergo G1 phase arrest and apoptosis, thereby inhibiting cell proliferation and migration." (PMID 40118853, 2025). "In colorectal and thyroid cancers, CRIP1 silencing significantly inhibits cell proliferation, migration, and invasion." (PMID 40118853, 2025). "Among the markers of the CD34+CD117dim cells, cysteine-rich intestinal protein (CRIP1) belongs to the LIM/double-zinc finger protein family and is abnormally expressed in a variety of tumors, including breast cancer, colorectal tumors, and thyroid cancer." (PMID 35938037, 2022).
colorectal tumor (2 papers, 2019 to 2022). "Immunohistochemistry was performed to evaluate the expression of CRIP1 in paired normal and colorectal tumor specimens, as well as colorectal cell lines." (PMID 30850009, 2019).
idiopathic pulmonary fibrosis (2 papers, 2023 to 2025). Idiopathic pulmonary fibrosis (IPF) is a nonneoplastic pulmonary disease that is characterized by the formation of scar tissue within the lungs in the absence of any known cause. "Furthermore, the authors found unusual levels of certain genes in the red module associated with idiopathic pulmonary fibrosis, specifically S100A12, S100A9, CLEC4E, CRIP1, and IL1R2." (PMID 40782499, 2025).
leukemia (2 papers, 2022 to 2023). A malignant (clonal) hematologic disorder, involving hematopoietic stem cells and characterized by the presence of primitive or atypical myeloid or lymphoid cells in the bone marrow and the blood. "LSP1 was highly expressed in most leukemia cell lines (shown in the dotted box), while IL1R2, MPO, and CRIP1 were highly expressed in one or two leukemia cell lines." (PMID 37691822, 2023). "Additionally, as CRIP1 and LSP1 are expressed on leukemia and cytotoxic immune cells, functional investigation of CRIP1 and LSP1 by AML cells or immune cells from TIME in vitro and in vivo assays will consolidate the dual-targeting treatment strategy for AML." (PMID 37691822, 2023). "LSP1 and CRIP1 were elevated in exhausted CD8+ T cells, indicating that dual-targeting them may reverse the dysfunction of CD8+ T cells and inhibit leukemia growth to delay disease progression; however, further work is required to be carried out." (PMID 37691822, 2023).
osteoarthritis (2 papers, 2025). A noninflammatory degenerative joint disease occurring chiefly in older persons, characterized by degeneration of the articular cartilage, hypertrophy of bone at the margins and changes in the synovial membrane. "CRIP1 is a differentially expressed gene in the synovium and blood of patients with osteoarthritis and has diagnostic value for osteoarthritis." (PMID 40118853, 2025).
periodontitis (2 papers, 2022 to 2026). An acute or chronic inflammatory process that affects the tissues that surround and support the teeth. "An ELISA was conducted on the plasma of the healthy and periodontitis groups to measure changes in CRIP1 and IFITM1 protein concentrations, and compared with those of the inflammatory markers TNF-α, CRP, and ESR." (PMID 36329504, 2022). "We analyzed pan-cellular differentially expressed genes caused by periodontitis and found that most cell types showed a significant increase in CRIP1, which was further supported by the increased levels of plasma CRIP1 observed in patients with periodontitis." (PMID 36329504, 2022). "Although there was a similar concentration of the three inflammatory indicators between the healthy and periodontitis groups, we found a difference in CRIP1 and IFITM1 levels." (PMID 36329504, 2022). "Furthermore, we investigated the relationship between CRIP1 expression and inflammatory gene profiles using single cell RNA sequencing data of peripheral mononuclear cells from healthy individuals and periodontitis patients." (PMID 41972184, 2026). "Taken together, the upregulation of CRIP1 may be a predictive marker for systemic inflammation induced by periodontitis." (PMID 36329504, 2022). "Remarkably, the expression of the CRIP1 gene was differentially increased in almost every cell type in the periodontitis samples and the concentration of plasma CRIP1 protein also increased in the periodontitis group." (PMID 36329504, 2022). "Moreover, CRIP1 levels reflect periodontitis-induced inflammation more sensitively than typical indicators." (PMID 36329504, 2022). "An increase in cysteine-rich protein 1 (CRIP1) in patients with periodontitis is observed in all types of innate immune cells, and CRIP1 levels after therapy are similar to that in healthy controls, suggesting that CRIP1 may be an important factor in maintaining chronic inflammation." (PMID 36329504, 2022). "The ROC curves showed that the area under the ROC curve (AUC) for CRIP1 and IFITM1 in the healthy and periodontitis groups was 0.94 and 0.66, respectively (both p-values < 0.001)." (PMID 36329504, 2022).
uterine fibroids (2 papers, 2023). "Induction of a known fibroid subtype mutation in CRIP1 + /PECAM1- cells and their subsequent development into fibroid-like cells, could advance our understanding of fibroid etiology based on the hypothesis that a dysregulated MyoSPC is the origin of uterine fibroids." (PMID 37400623, 2023). "Subsequent stem cell assays confirmed that CRIP1+ cells have MSC properties, and further studies are underway to determine whether these cells could be a cell of origin for uterine fibroids." (PMID 37400623, 2023).
acute monocytic leukemia (1 paper, 2022). Acute monoblastic leukemia (AML-M5), is one of the most common subtypes of acute myeloid leukemia (AML) that is either comprised of more than 80% of monoblasts (AML-M5a) or 30-80% monoblasts with (pro)monocytic differentiation (AML-M5b). "From the CCLE database, the CRIP1 expression of AML cell lines was analyzed with the highest expression in THP-1 (acute monocytic leukemia) and lowest in NB-4 (acute promyelocytic leukemia, APL)." (PMID 35938037, 2022).
Arthritis (1 paper, 2026). Inflammation of a joint. "Peptide-based interventions targeting CRIP1 K49 lactylation effectively inhibited synovial hyperplasia and disease severity in both Collagen II-induced arthritis (CIA) and humanized NSG chimeric models." (PMID 42258744, 2026).
cutaneous melanoma (1 paper, 2025). A primary melanoma arising from atypical melanocytes in the skin. "In cutaneous melanoma, CRIP1 expression levels are lower than in normal tissues and are associated with poor prognosis, inhibiting the proliferation, migration and invasion of melanoma cells in vitro." (PMID 40118853, 2025). "However, CRIP1 inhibits the progression of cutaneous melanoma by inhibiting the implementation of mitochondrial function." (PMID 40118853, 2025).
esophageal squamous cell carcinoma (1 paper, 2025). Esophageal squamous cell carcinoma (ESCC) is a type of esophageal carcinoma (EC) that can affect any part of the esophagus, but is usually located in the upper or middle third. "Studies in esophageal squamous cell carcinoma have found that CRIP1 promoter hypermethylation, and complete silencing of CRIP1 promotes tumor progression." (PMID 40118853, 2025).
fibroid (1 paper, 2023). "Inducing common mutations observed in fibroids in CRIP1+/PECAM1- myometrium cells, such as MED12 (exon 2, 131 G > A, G44D) or overexpression of HMGA2, could provide insight into fibroid etiology and models to evaluate alternative therapeutics." (PMID 37400623, 2023).
infarcts (1 paper, 2025). "Notably, LTBP1 and CRIP1, along with C1QC and PRSS23 (linked to WMH and infarcts) and CEMIP and ELN (associated with WMH and microbleeds), showed strong co-localization with ThioS- positive vascular amyloid deposits, but not with parenchymal plaques." (PMID 41282800, 2025). "Since CRIP1 protein levels in CSF were positively associated with CAA pathology and all three vascular neuroimaging abnormalities (WMH, microbleeds, and infarcts) in ADNI, we next focused on the genetic variant linked to CSF CRIP1 variation, the protein quantitative trait locus (pQTL) rs35590487." (PMID 41282800, 2025).
invasive breast carcinoma (1 paper, 2013). A carcinoma that infiltrates the breast parenchyma. "We show that in invasive breast carcinomas, CRIP1 expression is associated with not only HER2 expression but also the metastases-free survival of patients, with a more favorable prognosis for patients with high CRIP1 expression." (PMID 23570421, 2013).
invasive ductal breast carcinoma (1 paper, 2013). The most common type of invasive breast carcinoma, accounting for approximately 70% of breast carcinomas. "Using FFPE tissues from invasive ductal breast carcinomas (IDC), we show an association between CRIP1 expression and histopathological parameters and, the clinical course of the disease." (PMID 23570421, 2013). "To elucidate the prognostic impact of CRIP1, we analyzed tissues from 113 primary invasive ductal breast carcinomas using immunohistochemistry." (PMID 23570421, 2013).
ischemia (1 paper, 2020). A hypoperfusion of the BLOOD through an organ or tissue caused by a PATHOLOGIC CONSTRICTION or obstruction of its BLOOD VESSELS, or an absence of BLOOD CIRCULATION. "Ischemic damage decreased 14-3-3η expression in all hippocampal sub-regions 4 days after ischemia; however, the treatment of Tat-CRIP1 ameliorated the reduction of 14-3-3η expression." (PMID 32756411, 2020).
liver cirrhosis (1 paper, 2025). "In addition, CRIP1 is also highly expressed in liver cirrhosis, and single-cell transcriptome results show that CRIP1 is the core driver gene of hepatic stellate cell activation." (PMID 40118853, 2025).
metastatic colorectal cancer (1 paper, 2021). "In metastatic colorectal cancer (CRC), CRIP1 was overexpressed and downregulation of CRIP1 was found to inhibit cell migration and invasion in the cell lines SW620 and HT29." (PMID 34413913, 2021).
nasopharyngeal carcinoma (1 paper, 2023). A carcinoma arising from the nasopharyngeal epithelium. "CRIP1, on the other hand, is strongly downregulated and has been identified as a biomarker of EBV-associated nasopharyngeal carcinoma." (PMID 38077135, 2023).